SIK1 (salt inducible kinase 1)
Diseases named in the same sentence as SIK1 in open-access papers (continued):
Sharing a sentence is not in itself a finding about the gene and the disease.
cardiovascular disease (2 papers, 2024 to 2026). "Future studies should investigate how Sik1 regulates the dialogue between neurons and microglia, which may reveal novel mechanisms for neuroinflammatory components of cardiovascular disease." (PMID 41543628, 2026). "Moreover, QiShenYiQi, a traditional Chinese medicine for cardiovascular disease, has been found to alleviate renal damage through downregulating alpha-1D adrenergic receptors and upregulating salt-inducible kinase 1 in the mice model." (PMID 38345042, 2024).
adenocarcinoma (1 paper, 2014). A common cancer characterized by the presence of malignant glandular cells. "In the present study we show that gastrin-mediated signalling, known to involve the Gq/G11-coupled CCK2 receptor and signalling pathways like PI3K-PKB/Akt, PKC and MEK-ERK1/2, induces transient SIK1 expression in adenocarcinoma cells." (PMID 25384047, 2014). "We show that gastrin, known to signal through the Gq/G11-coupled CCK2 receptor, induces SIK1 expression in adenocarcinoma cells, and that transcriptional activation of SIK1 is negatively regulated by the Inducible cAMP early repressor (ICER)." (PMID 25384047, 2014). "Microarray mRNA profiling of gastrin-treated pancreas derived adenocarcinoma cells (AR42J) demonstrated that gastrin transiently activates Sik1 gene expression (Accession number: GSE32869)." (PMID 25384047, 2014). "The aim of this study was to examine the role of SIK1 in gastrin responsive adenocarcinoma cell lines AR42J, AGS-GR and MKN45." (PMID 25384047, 2014).
metabolic disorders (1 paper, 2019). "In the diabetic conditions, normal regulation of gluconeogenesis and lipogenesis is disrupted; hence the SIK1/CRTC2 and SIK1/SREBP-1c pathways may serve as therapeutic targets to modulate metabolic disorders in diabetic patients with NAFLD." (PMID 31233505, 2019).
SIK1 also shares sentences with these, for which no sentence is quoted: chronic kidney disease (2 papers); colitis (2); hyperlipidaemia (2); non-small cell lung carcinoma (2); acute kidney injury (1); adrenal hypoplasia (1); anencephaly (1); anxiety disorder (1); autoimmune disease (1); bladder (1); cervical squamous cell carcinoma (1); depression (1); desmoplastic small round cell tumor (1); Epileptic Seizures (1); fibromyalgia (1); glioma (1); Hyperinsulinemia (1); hypoglycaemia (1); inflammation (1); lipid metabolism disorder (1); liver cancer (1); long-QT syndrome 5 (1); muscle atrophy (1); myelodysplastic syndrome (1); neurodevelopmental disorder (1); Ohtahara syndrome (1); osteoarthritis (1); retinitis pigmentosa (1); Sepsis (1); skin cancer (1).
A further 1 disease shares a sentence with SIK1 in 1 paper.